NR1H5P (nuclear receptor subfamily 1 group H member 5, pseudogene)
Synonyms: Fxrb; NR1H5
Gene: Unitary pseudogene on chromosome 1 (114,837,227 to 114,851,453, forward strand). Ensembl gene ENSG00000227970.
Diseases named in the same sentence as NR1H5P in open-access papers:
NR1H5P is named in the same sentence as 1 disease in open-access papers, as found by Europe PMC text mining. Sharing a sentence is not in itself a finding about the gene and the disease.
NR1H5P shares sentences with these, for which no sentence is quoted: intestinal tumor (1 paper).